PDE1C (phosphodiesterase 1C)
Diseases named in the same sentence as PDE1C in open-access papers (continued):
Sharing a sentence is not in itself a finding about the gene and the disease.
oral cancer (1 paper, 2021). "Future analysis on the activity regulation of PDE1C in Drosophila and human oral cancer cell platforms will provide a further insight into the molecular mechanisms underlying the pathophysiology of oral cancer." (PMID 34335946, 2021). "Our results indicate that miR-133-dependent downregulation of PDE1C is likely correlated with promoted tissue growth in Drosophila as well as accelerated expression of EMT phenotypes in oral cancer cells, presumably underlying more pronounced aggressive cellular behaviors." (PMID 34335946, 2021). "The role of such convergence on PDE1C-mediated regulation of EMT in the pathophysiology of oral cancer awaits further investigations." (PMID 34335946, 2021). "Validation of miR-133-dependent targeting of PDE1C in both Drosophila wing discs and human oral cancer cells provides a further support to our combinational approach in the process of functional characterization of novel molecules implicated in human diseases." (PMID 34335946, 2021). "As the first step of visualizing miR-133-dependent regulation of PDE1C, we monitored the level of endogenous miR-133 in oral cancer cells." (PMID 34335946, 2021). "Taken together, our mammal-to-Drosophila-to-mammal approach successfully validates targeting of PDE1C by miR-133 both in vivo and in vitro, underlying the promoted EMT phenotypes and potentially influencing the prognosis of oral cancer patients." (PMID 34335946, 2021). "In summary, we demonstrate miR-133-dependent targeting of PDE1C in both Drosophila melanogaster and human oral cancer cells." (PMID 34335946, 2021). "Our findings indicate a shared targeting of phosphodiesterase 1C (PDE1C), a member of phosphodiesterase family, by miR-133 in both Drosophila tissues and human oral cancer cells, underlying promoted tissue growth and more pronounced development of EMT phenotypes." (PMID 34335946, 2021). "Our results demonstrate a central role of PDE1C in the process of EMT in oral cancer." (PMID 34335946, 2021). "Furthermore, the elevated level of miR-133 and its targeting of PDE1C was positively correlated with enhanced migrative ability of oral cancer cells treated with LPS, along with the molecular signature of a facilitated EMT process induced by LPS and TGF-β." (PMID 34335946, 2021).
prostate carcinoma (1 paper, 2022). A carcinoma that arises from epithelial cells of the prostate gland. "There were no previous descriptions for the fusions NAIP:OCLN, PDE1C:DNAJC6, KANSL1:ARL17B, FOXP2:CREM, and AHSA1:DLG3 in the context of prostate cancer." (PMID 35625354, 2022).
synucleinopathies (1 paper, 2017). "In conclusion, this work identifies that inhibition of PDE1A and/or PDE1C might be useful in the prevention or treatment of synucleinopathies." (PMID 28904388, 2017).
tumor (8 papers, 2012 to 2025). "A recent study analyzing genetic variants in the calcium signaling pathway pointed to the PDE1C gene as a key gene contributing to CRC through changes in the tumor microenvironment." (PMID 39518949, 2024). "In melanoma cells, PDE1C is overexpressed, and its inhibition by vinpocetine significantly reduces tumor growth." (PMID 41179677, 2025). "We investigated the correlation between PDE1C expression levels and 22 different kinds of tumor-infiltrating immune cells." (PMID 36824126, 2023). "Several genes previously reported as subgroup-specific drivers or tumor lineage markers, such as PTCH1, PDE1C, and ST18 in SHH and OTX2, EOMS, and LMX1A in G3, were recovered and detected as DEGs exclusively in GNP and RL, respectively." (PMID 41029754, 2025). "The high mRNA expression level of the PDE1C group had a higher immune score and a higher ESTIMATE (microenvironment) score, signifying a different tumor microenvironment from the low mRNA expression level of the PDE1C group (P < 0.05)." (PMID 36824126, 2023). "We therefore combined the expression values for the genes identified above (DDIT3, HOXD10, PDE1C, PLS3, PTEN and TUSC3) into a single value per tumor sample, termed 'GNS signature score'." (PMID 23046790, 2012). "On the one hand, ADRB2 (SMD = −1.46; 95% CI −2.02, − 0.91; P < 0.01), PDE1C (SMD = −0.75; 95% CI – 1.11, −0.39; P < 0.01) and PTGER3 (SMD = −0.58; 95% CI −1.08; −0.07; P < 0.01) were down-regulate in the cancer groups, which might be a tumor suppressor gene." (PMID 34646828, 2021).
cancer (4 papers, 2021 to 2024). A tumor composed of atypical neoplastic, often pleomorphic cells that invade other tissues. "Phosphodiesterase 1 (PDE1s: PDE1A; PDE1B; PDE1C) targets second messengers (cAMP and cGMP) to regulate diverse physiological processes, with limited exploration in cancer." (PMID 38962317, 2024). "It is plausible that the level of endogenous PDE1C could vary to a significant degree among different types of cancer cells." (PMID 34335946, 2021). "According to the DTI predictions, PDE1C could be associated with felodipine (DB01023), bepridil (DB01244), nicardipine (DB00622), and roflumilast (DB01656), which are drugs used in chemotherapy for cancer." (PMID 36262151, 2022). "In addition, downregulation of Pde1c in Drosophila wing discs resulted in a noticeable increase in their size via increased cell proliferation, further supporting the idea of PDE1C as an inhibitory signal for cancer progression." (PMID 34335946, 2021). "Downregulation of PDE1C by miR-133 is positively correlated with accelerated expression of EMT, a process central to acquisition of aggressive behaviors of cancer cells." (PMID 34335946, 2021).
PDE1C also shares sentences with these, for which no sentence is quoted: adenoma (1 paper); adrenocortical adenoma (1); Alzheimer disease (1); aneurysm (1); arrhythmogenic right ventricular cardiomyopathy (1); basal cell carcinoma (1); chronic obstructive pulmonary disease (1); Down syndrome (1); glioma (1); Huntington disease (1); Hypertension (1); hypertrophic cardiomyopathy (1); ischemic heart disease (1); Parkinson disease (1); rheumatoid arthritis (1); type 2 diabetes (1).